PCYT1A (phosphate cytidylyltransferase 1A, choline)
Description:
Catalyzes the key rate-limiting step in the CDP-choline pathway for phosphatidylcholine biosynthesis.
Synonyms: CTPCT; PCYT1; CT; CCTalpha; CCTA; CGL5; CTA; SMDCRD
Tractability: Antibody: UniProt places it where antibodies can reach, with medium confidence. PROTAC: UniProt records ubiquitination sites on it; ubiquitination databases record sites on it; its protein half-life has been measured; a small molecule that binds it is known.
Target class: Enzyme; Transferase
Gene: Protein-coding gene on chromosome 3 (196,214,222 to 196,287,957, reverse strand). Ensembl gene ENSG00000161217.
Subcellular location: Cytoplasm, cytosol; Membrane; Endoplasmic reticulum membrane; Nucleus
Subcellular location (Human Protein Atlas): Nucleoplasm; Cytosol
Pathways (Reactome):
Metabolism: Synthesis of PC
Gene Ontology:
Molecular function: choline-phosphate cytidylyltransferase activity; identical protein binding; protein binding; phosphatidylcholine binding; calmodulin binding; catalytic activity; lipid binding; molecular function inhibitor activity; protein homodimerization activity
Biological process: CDP-choline pathway; phosphatidylcholine biosynthetic process; B cell proliferation; isotype switching; phosphatidylcholine metabolic process
Cellular component: endoplasmic reticulum; endoplasmic reticulum membrane; nucleus; glycogen granule; membrane; cytosol; nuclear envelope
Genetic constraint (gnomAD): Loss-of-function variants: 10 observed, 18.17 expected, observed/expected ratio (o/e) 0.55, 90% interval 0.34 to 0.93. The upper end of that interval is the gene's LOEUF score, 0.93, which puts it in group 3 of 6, group 1 being the genes least tolerant of losing a copy. Missense variants: 258 observed, 274.18 expected, observed/expected ratio (o/e) 0.94, 90% interval 0.85 to 1.04. Synonymous variants: 119 observed, 106.18 expected, observed/expected ratio (o/e) 1.12, 90% interval 0.96 to 1.3.
Gene-disease validity (ClinGen):
ClinGen rates the evidence that PCYT1A causes each of these diseases.
spondylometaphyseal dysplasia-cone-rod dystrophy syndrome (autosomal recessive): Definitive.
Homologues: Orthologues: macaque PCYT1A (99% identical), rabbit PCYT1A (97% identical), rat Pcyt1a (96% identical), mouse Pcyt1a (96% identical), guinea pig PCYT1A (95% identical), dog PCYT1A (95% identical), pig PCYT1A (93% identical), tropical clawed frog pcyt1a (86% identical), chimpanzee PCYT1A (81% identical), zebrafish pcyt1aa (80% identical), zebrafish pcyt1ab (73% identical), Drosophila melanogaster Pcyt1 (50% identical), and 3 more. Paralogues in human: PCYT1B (68% identical), PCYT2 (23% identical).
Diseases named in the same sentence as PCYT1A in open-access papers:
PCYT1A is named in the same sentence as 43 diseases in open-access papers, as found by Europe PMC text mining. Sharing a sentence is not in itself a finding about the gene and the disease. The quoted sentences say what the papers report.
spondylometaphyseal dysplasia (7 papers, 2019 to 2026). Spondylometaphyseal dysplasias are a heterogeneous group of disorders associated with walking and growth disturbances that become evident during the second year of life. "In humans, hypomorphic PCYT1A variants cause diverse disorders, including retinal dystrophy, lipodystrophy with fatty liver, and spondylometaphyseal dysplasia." (PMID 42079169, 2026). "PCYT1A loss-of-function variants cause spondylometaphyseal dysplasia with cone–rod dystrophy (SMD-CRD) in humans." (PMID 36553621, 2022). "In humans, different variants in the PCYT1A gene may cause three discernible phenotypes: spondylometaphyseal dysplasia with cone–rod dystrophy (SMD-CRD), lipodystrophy and isolated retinal dystrophy." (PMID 36553621, 2022). "Finally, inactivating mutations in PCYT1A gene have been linked to several human pathologies, including retinal dystrophy, spondylometaphyseal dysplasia and lipodystrophy." (PMID 31418690, 2019). "Pathogenic variants in the PCYT1A gene, encoding CTP-phosphocholine cytidylyltransferase, a key enzyme in the de novo phosphatidylcholine biosynthesis, cause spondylometaphyseal dysplasia with cone-rod dystrophy (MIM #608940) with normal development." (PMID 30779713, 2019).
lymphoma (3 papers, 2019 to 2024). A malignant (clonal) proliferation of B- lymphocytes or T- lymphocytes which involves the lymph nodes, bone marrow and/or extranodal sites. "In B-lymphoma cells, c-Myc activates the transcription of the key enzyme phosphate cytidylyltransferase 1 choline-α (PCYT1A) and PCYT1A upregulation prevents lymphoma cells to undergo a mitophagy-dependent necroptosis." (PMID 31121959, 2019). "As in DLBCL lymphomas, we found in our mAITL mouse model that the neoplastic lymphoma T cells showed a significant upregulation of Pcyt1a, which might represent in addition to Chokα, another target in choline metabolism for anti-cancer treatment." (PMID 38321568, 2024). "Indeed, inhibition of Pcyt1a exhibited anti-lymphoma activity on glioblastoma and DLBCL in vitro and in vivo." (PMID 38321568, 2024). "In this context, berberine effectively suppressed DLBCL cancer cells growth by inhibiting the MYC-driven downstream effector PCYT1A, and inducing mitophagy-dependent necroptosis, thus being eventually considered as a promising anticancer agent to treat MYC-overexpressing lymphomas." (PMID 33467668, 2021). "The authors of the study showed that PCYT1A was overexpressed in 44% of the analyzed DLBCL patients and that PCYT1A overexpression occurred in parallel with the enhanced gene and protein expression of MYC, an oncogene mostly involved in lymphoma cell chemoresistance." (PMID 33467668, 2021).
diffuse large B-cell lymphoma (2 papers, 2021 to 2025). "Berberine induces mitophagy-dependent necrosis and inhibits cancer cell proliferation by inhibiting the expression of PCYT1A in diffuse large B-cell lymphomas." (PMID 34065886, 2021).
liver fibrosis (2 papers, 2019 to 2022). "The results of RT-PCR in liver tissue of rats with liver fibrosis showed that the expression of CYP1A2 and PCYT1A was up-regulated and the expression of CYP1B1 was down-regulated in AR treatment groups, which was consistent with the previously reported results." (PMID 31467589, 2019). "Metabolomics combined with network pharmacology was used for the first time to clarify that the treatment of AR on liver fibrosis, which is related to the regulation of arachidonic acid metabolism and ether lipid metabolism by modulating the expression of CYP1A2, CYP1B1 and PCYT1A." (PMID 31467589, 2019). "Taken together, our study found that AR could be involved in the regulation of arachidonic acid metabolism and ether lipid metabolism by regulating the expression of CYP1A2, PCYT1A and CYP1B1, thereby effectively improving liver fibrosis." (PMID 31467589, 2019).
lung carcinoma (2 papers, 2012 to 2022). "In this study, we also discovered that the PCYT1A gene expression level is significantly higher than the ERCC1 gene expression level in a certain population of lung cancer patient tissue samples." (PMID 23171216, 2012). "To examine the gene expression levels for ERCC1 and PCYT1A in different cancer patient tissue samples, we performed qPCR analysis on OriGene’s lung cancer qPCR TissueScan cDNA array panel, which contains cDNA from 24 lung cancer patient tissues." (PMID 23171216, 2012). "To facilitate our understanding of how much 8F1 nuclear immunostaining signal might be coming from 8F1-PCYT1A interaction, we wanted to compare the endogenous protein expression levels for PCYT1A and ERCC1 in lung cancer patients." (PMID 23171216, 2012).
prostate carcinoma (2 papers, 2024 to 2025). A carcinoma that arises from epithelial cells of the prostate gland. "Two genes (SYNPO2, PCYT1A) act in the Pi3K/Akt/mTOR pathway, involved in carcinogenesis of many tumours including colorectal-, gastric- and prostate cancer." (PMID 39543761, 2024).
dyslipidemia (1 paper, 2019). "Previous studies have reported that pcyt1a−/− mice exhibited severe fatty liver, dyslipidemia and other phenotypic characteristics." (PMID 31467589, 2019).
Hepatic steatosis (1 paper, 2019). Steatosis is a term used to denote lipid accumulation within hepatocytes. "And these results indicated that AR could modulate ether lipid metabolism to ameliorate CCl4-induced hepatic steatosis and fibrosis by regulating PCYT1A and MOGAT2." (PMID 31467589, 2019).
hepatocellular carcinoma (1 paper, 2022). A malignant tumor that arises from hepatocytes. "In conclusion, our study determined the prognostic and immunological roles of necroptosis‐related molecules such as TRAF2, PGAM5, ATG16L1, CADR9, PCYT1A, PARP2 and TLR2 in hepatocellular carcinoma." (PMID 35293027, 2022).
lung adenocarcinoma (1 paper, 2021). A carcinoma that arises from the lung and is characterized by the presence of malignant glandular epithelial cells. "PCYT1A, a choline-phosphate cytidylyltransferase, was reported to act as a tumor suppressor in lung adenocarcinoma." (PMID 34504059, 2021).
Obesity (1 paper, 2019). Accumulation of substantial excess body fat. "Overall, macrophage-specific Pcyt1a deletion did not affect ATM development, adipose tissue function and glucose metabolism in lean animals, but improved systemic glucose handling in Lepob/ob mice, the model of obesity in which we originally observed an induction of Pcyt1a in the ATM population." (PMID 31418690, 2019).
osteopetrosis (1 paper, 2024). Osteopetrosis, also known as marble bone disease, is a descriptive term that refers to a group of rare, heritable disorders of the skeleton characterized by increased bone density on radiographs. "We therefore hypothesize that there was the same increased expression of the PCYT1A gene in osteopetrosis patients caused by CLCN7 mutation, which might account for the decrease level of phosphorylcholine." (PMID 40018371, 2024).
spina bifida (1 paper, 2006). A congenital neural tube defect in which vertebrae are not fully formed. "Given that periconceptional intake of choline has been associated with decreased risk of NTD-affected pregnancies, we investigated CHKA and PCYT1A genotypes on risk of spina bifida." (PMID 17184542, 2006). "Despite its limitations, this study provided initial data indicating a potential association between CHKA and PCYT1A gene variants and spina bifida risk." (PMID 17184542, 2006). "This study investigated whether single nucleotide polymorphisms (SNPs) in human choline kinase A (CHKA) gene and CTP:phosphocholine cytidylytransferase (PCYT1A) gene were risk factors for spina bifida." (PMID 17184542, 2006). "Future studies of additional SNPs within the CHKA and PCYT1A genes should be investigated as potential predictors of spina bifida risks." (PMID 17184542, 2006). "Effect estimates (odds ratios) for spina bifida-affected pregnancies associated with CHKA SNPs hCV1562388 (A>C) and hCV1562393(C>G), PCYT1A SNPs rs939883 (T>A) and rs3772109 (T>C), California 1989–1991." (PMID 17184542, 2006). "Effect estimates (odds ratios) for spina bifida-affected pregnancies associated with maternal choline intake, CHKA SNP hCV1562388 (A>C), hCV1562393(C>G), PCYT1A SNPs rs939883 (T>A) and rs3772109 (T>C) genotypes." (PMID 17184542, 2006).
cancer (10 papers, 2012 to 2025). A tumor composed of atypical neoplastic, often pleomorphic cells that invade other tissues. "We found increased expression of the rate-limiting enzyme of PtdCho synthesis, PCYT1A, in cancer cells undergoing autophagy and showed that the loss of its activity results in the inability of cells to maintain autophagosome biogenesis." (PMID 31517566, 2020). "In DLBCL cells, berberine promoted mitophagy-dependent necroptosis by inducing the formation of the RIP1/RIP3/MLKL necrosome complex and mRNA degradation of PCYT1A (phosphate cytidylyltransferase 1 alpha), thus reducing its expression in cancer cells." (PMID 33467668, 2021). "While the Kennedy pathway is required for normal cell function and thus targeting PCYT1A in cancer may lead to unfavorable side effects, two groups of adult patients with a functional mutation in PCYT1A have been identified." (PMID 31517566, 2020). "Furthermore, as new membrane synthesis is required for cellular growth and division in cancer, inhibition of PCYT1A may have an anti-tumor effect." (PMID 31517566, 2020). "A review of the literature on PC metabolism in various cancers revealed that FADS1, FASN, PCYT1A, LPCAT1, and PLD2 are involved in PC metabolism in multiple cancers." (PMID 40148316, 2025).
tumor (5 papers, 2012 to 2025). "Integrated lipidomic and functional analyses revealed that TFE3 activation drives phosphatidylcholine overproduction via direct upregulation of phosphate cytidylyltransferase 1A (PCYT1A), establishing a tumor‐promoting feedforward loop." (PMID 40917018, 2025). "These myoCAFs drive resistance via TFE3‐mediated autophagy and PCYT1A‐led phosphatidylcholine overproduction, creating a phospholipid‐rich niche that activates tumor HSP90/HIF1A, promoting stemness and revealing actionable therapeutic targets for HSPC." (PMID 40917018, 2025). "TFE3 overexpression in P4+TFE3+ CAF enhanced tumor sphere formation in LNCaP/22Rv1 cells through PCYT1A‐mediated PC secretion, whereas dual TFE3 overexpression and PCYT1A knockdown (oeTFE3 + shPCYT1A) in P4+TFE3+ CAF reduced spheres." (PMID 40917018, 2025). "Mechanistically, TFE3 activation upregulates phosphate cytidylyltransferase 1A (PCYT1A), driving phosphatidylcholine overproduction that activates the HSP90/HIF1A axis in tumor cells to enforce stemness." (PMID 40917018, 2025). "The stromal specificity of this pathway is underscored by the absence of TFE3/PCYT1A co‐expression in epithelial tumor cells, suggesting CAFs create a lipid‐rich niche that enables tumor cell persistence under ENZ pressure." (PMID 40917018, 2025).
PCYT1A also shares sentences with these, for which no sentence is quoted: lipodystrophy (6 papers); cone-rod dystrophy (3); Retinal dystrophy (3); generalized lipodystrophy (2); Insulin resistance (2); retinal degeneration (2); acquired generalized lipodystrophy (1); acquired lipodystrophy (1); bacterial infection (1); CANDLE syndrome (1); cleft palate (1); colorectal cancer (1); diabetes (1); familial partial lipodystrophy (1); glioblastoma (1); infection (1); lipid metabolism disorders (1); Macrocephaly (1); mandibuloacral dysplasia (1); microcephaly (1); Micrognathia (1); multiple lipomatosis (1); ocular hypertelorism (1); orofacial clefting (1); pancreatic cancer (1); partial lipodystrophy (1); primary ciliary dyskinesia (1); retinal disease (1).